CARF (calcium responsive transcription factor)
Description:
Acts as a transcriptional activator that mediates the calcium- and neuron-selective induction of BDNF exon III transcription. Binds to the consensus calcium-response element CaRE1 5'-CTATTTCGAG-3' sequence.
Synonyms: ALS2CR8; FLJ21579; NYD-SP24
Tractability: No criterion of Open Targets' tractability assessment is met for any kind of drug.
Gene: Protein-coding gene on chromosome 2 (202,912,214 to 202,988,263, forward strand). Ensembl gene ENSG00000138380.
Subcellular location: Nucleus
Subcellular location (Human Protein Atlas): Vesicles; Cytosol; Nucleoli fibrillar center
Gene Ontology:
Molecular function: DNA binding; DNA-binding transcription activator activity, RNA polymerase II-specific; protein binding; DNA-binding transcription factor activity, RNA polymerase II-specific; RNA polymerase II cis-regulatory region sequence-specific DNA binding; DNA-binding transcription factor activity
Biological process: cellular response to calcium ion; regulation of transcription by RNA polymerase II; positive regulation of transcription by RNA polymerase II
Cellular component: nucleus
Genetic constraint (gnomAD): Loss-of-function variants: 31 observed, 53.51 expected, observed/expected ratio (o/e) 0.58, 90% interval 0.43 to 0.78. The upper end of that interval is the gene's LOEUF score, 0.78, which puts it in group 3 of 6, group 1 being the genes least tolerant of losing a copy. Missense variants: 609 observed, 693.74 expected, observed/expected ratio (o/e) 0.88, 90% interval 0.82 to 0.94. Synonymous variants: 209 observed, 237.87 expected, observed/expected ratio (o/e) 0.88, 90% interval 0.78 to 0.99.
Homologues: Orthologues: chimpanzee CARF (99% identical), macaque CARF (92% identical), rabbit CARF (85% identical), pig CARF (84% identical), dog CARF (84% identical), guinea pig CARF (83% identical), rat Carf (73% identical), mouse Carf (71% identical), tropical clawed frog carf (50% identical), zebrafish carf (40% identical).
Diseases named in the same sentence as CARF in open-access papers:
CARF is named in the same sentence as 25 diseases in open-access papers, as found by Europe PMC text mining. Sharing a sentence is not in itself a finding about the gene and the disease. The quoted sentences say what the papers report.
migraine (3 papers, 2020 to 2023). "For example, the reported migraine-associated signal near calcium responsive transcription factor (CARF) displayed colocalization with neurobeachin like 1 (NBEAL1) expression in all three arterial tissues." (PMID 31917787, 2020). "The majority of the identified variants were found in genes previously associated with migraine (LRP1, ECM1, CARF, CTIF, RNF213, APOE, SLC35D2), with two different rare LRP1 variants each identified in two unrelated children with vertigo." (PMID 37107589, 2023). "The resulting subnetwork included 9 genes: migraine-associated genes APOE, LRP1, CARF, CTIF, RNF213, and ECM1; LAMA2, which is associated with vestibular anomalies in mice; and the neurodevelopment-associated genes MYO5A and KLC2." (PMID 37107589, 2023). "Exome sequencing revealed that she had three rare variants in migraine genes, LRP1 c.13471G>C (p.(Asp4491His)), ECM1 c.1126T>C (p.(Cys376Arg)), and CARF c.1718C>T (p.(Ser573Phe))." (PMID 37107589, 2023). "For example, of the five genes (CARF, ICAIL, NBEAL1, FAM117B, and WDR12) at the rs138556413 locus, ICAIL and NBEAL1 have the strongest TWAS p value with migraine as compared to other genes." (PMID 37245199, 2023).
cerebral small vessel disease (1 paper, 2022). Cerebral small vessel disease is the term currently used to pathological processes that affect the brain parenchymal circulation (arterioles, capillaries, and veins). "SNP rs116426890 is intronic to ABI2 and is linked to the expression of CARF, ICA1L, FAM117B, and NBEAL1 which are associated with both white matter hyperintensities and fractional anisotropy, predictors of cerebral small vessel disease which is involved in strokes and vascular dementia." (PMID 36684006, 2022).
fibrosarcoma (1 paper, 2018). A malignant mesenchymal fibroblastic neoplasm affecting the soft tissue and bone. "We found that invasive ovarian (SKOV-3), lung (H-1299), and fibrosarcoma (HT-1080) cell lines derived from secondary metastatic tumor site possessed high level of CARF expression." (PMID 29748568, 2018).
Hepatic steatosis (1 paper, 2023). Steatosis is a term used to denote lipid accumulation within hepatocytes. "Deficiency of CARF exerts multiple downstream effects leading to perturbation of ER homeostasis and oxidative stress, resulting in fat deposition in the hepatocytes and development of hepatic steatosis." (PMID 37048142, 2023). "Downregulation of CARF in both in vivo and in vitro models of hepatic steatosis raises the possibility that loss of function of CARF might regulate hepatic fat accumulation." (PMID 37048142, 2023). "To determine whether deficiency of CARF induces chronic ER stress leading to hepatic steatosis, we inhibited ER stress in CARF-depleted cells through treatment with TUDCA, a chemical chaperone capable of neutralizing ER stress." (PMID 37048142, 2023). "We can conclude that CARF is a critical regulator of the development and progression of hepatic steatosis, as depicted in the model." (PMID 37048142, 2023). "In this study, using our established in vivo as well as in vitro models of hepatic steatosis, we elucidated some of the molecular mechanisms by which CARF mitigates HFD-induced hepatic fat accumulation." (PMID 37048142, 2023). "Overall, these data suggest that by regulating HFD-induced induced hepatic ER stress and oxidative stress, CARF plays a pivotal role in protecting hepatic steatosis." (PMID 37048142, 2023). "Altogether, we conclude that excess fat-induced reduction of CARF dysregulates ER functions and lipid metabolism leading to hepatic steatosis." (PMID 37048142, 2023). "By using in vitro and in vivo models of hepatic steatosis, global transcriptome analysis, and AAV-mediated overexpression of CARF, we unveil a novel role of CARF in the process of hepatic steatosis." (PMID 37048142, 2023). "Given that CARF expression goes down in both in vivo as well as in vitro models of hepatic steatosis, we assumed that CARF has a protective role against fat deposition in hepatocytes." (PMID 37048142, 2023). "Intriguingly, CARF overexpression in HFD-fed mice significantly decreased hepatic steatosis." (PMID 37048142, 2023). "Next, we sought to assess whether hepatic CARF overexpression (CARF-OE) suppresses the HFD-induced hepatic steatosis in mice." (PMID 37048142, 2023). "Since dysregulation of ER functions plays a crucial role in the onset of hepatic steatosis, we sought to show whether CARF overexpression in HFD-fed mice can reverse the expression of the ER-stress-responsive gene." (PMID 37048142, 2023). "Therefore, our results suggest that downregulation of CARF via FFA-mediated stress provokes ER stress, oxidative stress, and apoptosis that leads to hepatic steatosis." (PMID 37048142, 2023).
Infertility (1 paper, 2020). "CARF−/− male mice exhibited subfertility at 8–16 weeks of age, and when they aged to 52–week, they were completely infertile." (PMID 33298864, 2020). "Of note, our results showed that reactivation of Wnt signaling in CARF-null mice could only partially rescue infertility and SCO syndrome phenotypes." (PMID 33298864, 2020).
Insulin resistance (1 paper, 2023). Increased resistance towards insulin, that is, diminished effectiveness of insulin in reducing blood glucose levels. "Our results further demonstrated that overexpression of CARF alleviates HFD-induced insulin resistance assessed with ITT and GTT assay." (PMID 37048142, 2023).
liver diseases (1 paper, 2023). "Gain of function of CARF could alleviate FFA-induced metabolic stress in hepatocytes and associated liver diseases." (PMID 37048142, 2023).
lobular breast carcinoma (1 paper, 2018). "Consistent to mRNA expression data, invasive ductal tumors showed a higher level of CARF expression than the lobular breast carcinoma." (PMID 29748568, 2018).
melanoma (1 paper, 2023). A malignant, usually aggressive tumor composed of atypical, neoplastic melanocytes. "In a normal state (without SAMMSON) CARF via interaction with XRNA2 form a complex in the nucleoplasm, but in the presence of SAMMSON (in melanoma cells) the interaction between CARF and p32 was facilitated, which led to disrupted interaction between CARF and XRNA2." (PMID 37772815, 2023).
metastatic cancers (1 paper, 2018). A carcinoma which has spread from the original site of growth to another anatomic site. "Several other invasive malignancies such as sarcoma, lung, and prostate cancers, showed enrichment of CARF expression at Oncomine, suggesting clinical relevance of CARF upregulation with metastatic cancers." (PMID 29748568, 2018).
steatosis (1 paper, 2023). Increased lipid within the cytoplasm of cells. "Similarly, using in vitro cellular models of steatosis, we provide evidence that palmitate-induced lipotoxic stress leads to downregulation of CARF, suggesting that excessive FFA accumulation triggers the inhibition of CARF in hepatocytes." (PMID 37048142, 2023).
cancer (4 papers, 2013 to 2023). A tumor composed of atypical neoplastic, often pleomorphic cells that invade other tissues. "Recent studies implicated CARF as a positive regulator of the Wnt-β-catenin signaling pathway that has been shown to contribute to epithelial-mesenchymal transition in cancer, organ development in zebra fish, spermatogenesis in mice, and cancer stem cell renewal." (PMID 37048142, 2023). "Furthermore, the expression of CARF (collaborator of p14ARF)/CDKN2AIP mRNA that has been shown to regulate Wnt/β-catenin mediated EMT in cancer cells showed a significant decrease in Wi-ACAPE-treated cells." (PMID 35159054, 2022).
infection (3 papers, 2017 to 2025). The state of being infected such as from the introduction of a foreign agent such as serum, vaccine, antigenic substance or organism. "CARF effectors are typically dispensable for defense when the target is recognized early after infection, but absolutely essential when the phage transcript is recognized by the Cas10 complex in the latest stages of infection." (PMID 41292787, 2025). "In this way, CARF effectors turn type III CRISPR-Cas immunity into an abortive infection mode of defense that sacrifices the infected host to prevent the spread of the phage into the rest of the bacterial population." (PMID 41292787, 2025). "CARF and SAVED proteins have a plethora of catalytic activities associated with them, most of which seem to be geared towards killing the infected host (and thereby preventing viral progeny) to provide population-wide immunity; a mechanism known as abortive infection." (PMID 36282000, 2022). "Whereas only a handful of CARF and SAVED proteins have been studied so far, many of them seem to provoke abortive infection, aimed to kill the host and provide population-wide immunity." (PMID 36282000, 2022).
tumor (2 papers, 2013 to 2016). "Moreover, based on the expression pattern of CARF in HCC samples, it is very important to evaluate whether CARF might be served as tumor marker using HCC tissue array." (PMID 27829235, 2016).
infectious disease (1 paper, 2023). A disorder directly resulting from the presence and activity of a microbial, viral, or parasitic agent in humans. "TSPY4, OPN1LW, CARF, CCDC14, HNRNPCL4, SSX2B genes need further exploration as it has not been identified in any infectious disease, including the recent COVID-19 pandemic." (PMID 37644081, 2023).
CARF also shares sentences with these, for which no sentence is quoted: angina pectoris (1 paper); depression (1); diffuse large B-cell lymphoma (1); hepatocellular carcinoma (1); leukemia (1); sarcoma (1); Stroke (1); thyroid cancer (1); vascular dementia (1); Vertigo (1).